OTX1 (orthodenticle homeobox 1)
Diseases named in the same sentence as OTX1 in open-access papers (continued):
Sharing a sentence is not in itself a finding about the gene and the disease.
tumor (continued). "Homeoproteins orthodenticle OTX1 and OTX2 are neuronal transcription factors participating to adaptation during inflammation and underlying tumor growth both in the central nervous system and in the periphery." (PMID 32095330, 2020). "To further demonstrate the physiological relevance of OTX1 in LSCC in vivo, we investigated the effect of OTX1 on tumor growth using a xenotransplantation model." (PMID 32838760, 2020). "Mechanistically, the tumor suppressive properties of miR-4269 in PC were mediated by ZEB1/OTX1 pathway." (PMID 32484209, 2020). "Taken together, these results suggest that MIR100HG knockdown inhibited tumour growth by increasing miR-5590-3p expression to inhibit the OTX1/ERK/MAPK pathway in vivo." (PMID 33088216, 2020). "By the large, above results provided strong evidence that miR-4269 functioned as a tumor suppressor in PC progression via suppression of ZEB1-regulated OTX1." (PMID 32484209, 2020). "Otx1 was increased at the mRNA level, reflected by a high expression of Oxt1 protein in late-stage carcinoma CAFs, with the notion that also tumor cells expressed higher levels of Otx1 in the late stage." (PMID 31505876, 2019). "Elevated OTX1 expression promotes cell proliferation and tumor growth, suggesting that OTX1 could be a potential oncogene and a target for anticancer therapy." (PMID 40004500, 2025). "In addition, in vivo experiments demonstrated that OTX1 silencing resulted in a significant suppression of tumor growth in nude mice." (PMID 37780815, 2023). "In addition, OTX1 silencing induced cell cycle arrest in the G0/G1 phase and inhibited tumor growth in vivo." (PMID 37627900, 2023). "Further studies showed that OTX1 promoted the proliferation and migration of tumor cells." (PMID 34559577, 2021). "Besides, the expression of OTX1 in the para-carcinoma tissues and tumor tissues was detected by IHC, and the optical density value was analyzed by Image J Pro Plus software." (PMID 34559577, 2021). "Moreover, IHC assay suggested that OTX1 was successfully low-expressed, and the low expression of OTX1 decreased the expression of Ki67, thus suppressing tumor growth." (PMID 34559577, 2021). "Furthermore, in vivo experiments showed that OTX1 silencing significantly inhibited tumor growth in tumor-bearing mice." (PMID 34559577, 2021). "Moreover, miR-4516 exerted its tumor suppressor function via regulating OTX1 and overexpression OTX1 abrogated the effect of miR-4516 overexpression." (PMID 32549762, 2020). "Moreover, OTX1 knockdown cells-induced tumor samples showed reduced proliferation indices (Ki-67 positivity) compared to those formed by matched controls in Hep-2 and TU212 cells." (PMID 32838760, 2020). "In summary, these data suggested that knockdown of OTX1 inhibited tumor growth in vivo." (PMID 32838760, 2020). "OTX1 enhanced tumorigenicity and tumor growth both in vitro and in vivo." (PMID 32838760, 2020). "In addition, MIR100HG knockdown inhibited OTX1 expression by upregulating miR-5590-3p in vivo, thereby inhibiting tumour growth." (PMID 33088216, 2020). "Immunohistochemistry (IHC) analysis was used to assess OTX1 expression in tumour tissues." (PMID 33088216, 2020). "Next, we explored the potential role of OTX1 in tumor progression and metastasis." (PMID 32838760, 2020). "Knockdown of OTX1 inhibited tumor growth in a xenograft mouse model." (PMID 32838760, 2020). "We observed increased Otx1 expression in both CAFs and tumor cells." (PMID 31505876, 2019). "Taken together, we conclude that miR-4516 could function as a tumor suppressor via targeting OTX1." (PMID 32549762, 2020). "InccRCC, a 4-gene model comprising KIF4A, UBE2C, OTX1, and PPP2R2C showed great potential to distinguish tumour tissues from normal ones." (PMID 41361459, 2025). "In summary, the combined results from the in vitro and in vivo experiments consistently indicate a pivotal role of OTX1 in promoting PTC tumor growth and tumor progression." (PMID 37780815, 2023).
tumor (continued). "The knockdown of OTX1 expression by shRNA in human LSCC cells inhibited cell proliferation, migration and invasion in vitro and repressed tumor growth in vivo." (PMID 32838760, 2020). "Upon further examining the expression of OTX1 in TNBC tissues (n = 165) relative to various clinicopathological variables, we observed that OTX1 was markedly elevated in patients under 50 years and those with high tumor grades." (PMID 41019508, 2026). "Moreover, the overexpression of OTX1 promotes the HCC proliferation, migration, invasion, and tumor angiogenesis." (PMID 34532296, 2021).
cancer (18 papers, 2019 to 2025). A tumor composed of atypical neoplastic, often pleomorphic cells that invade other tissues. "In addition, the Kaplan–Meier survival analyses demonstrated a significant association between high OTX1 expression and reduced cancer-specific survival in PTC cases." (PMID 37780815, 2023). "The transcription factor OTX1 exemplifies pathway convergence, driving proliferation in various cancers through ERK, JAK/STAT, and Wnt/β-catenin activation." (PMID 41439026, 2025). "According to research, Orthodenticle Homeobox 1 (OTX1), a key regulatory factor for cancer development and progression, is a potential therapeutic target for tumors." (PMID 39077467, 2024). "Collectively, these findings underscore the significance of OTX1 as a potential prognostic indicator in various cancer types." (PMID 37780815, 2023). "Despite these insights into OTX1's involvement in several cancers, its specific role in PTC remains inadequately understood." (PMID 37780815, 2023). "In cancer cells, miR-4516 negatively regulates OTX1, and the ability of cell migration and invasion is reduced after down-regulation of OTX1." (PMID 35771766, 2022). "OTX1 (orthodenticle homeobox 1) is an important transcription factor involved in various diseases, such as cancers." (PMID 34559577, 2021). "Our results showed that OTX1 is a candidate gene for the diagnosis and prediction of BC, which promoted the growth and motility of cancer cells by regulating cell cycle-related pathways, thus exhibiting carcinogenic effects." (PMID 34559577, 2021). "With the continuous progression in studies, the role of OTX1 in the carcinogenesis and development of human cancer has drawn increasing attention." (PMID 32838760, 2020). "Orthodenticle homeobox 1 (OTX1) is a transcription factor that plays an important role in various human cancers." (PMID 32838760, 2020). "Of those, antibodies targeting the proteins orthodenticle homeobox 1 (Otx1) and hexamethylene bisacetamide inducible protein 1 (Hexim1) were of sufficient quality for validation in PyMT carcinoma sections." (PMID 31505876, 2019). "Given the importance of transcription factors in cellular processes and the emerging role of OTX1 in other cancers, investigating its role in PTC could provide valuable insights into the underlying molecular mechanisms driving PTC development and progression." (PMID 37780815, 2023). "In cancer cells, miR-4516 downregulates orthodenticle homeobox 1 (OTX1)-mediated cell invasion." (PMID 35771766, 2022). "OTX1 is a transcription factor that is commonly overexpressed in various cancers." (PMID 34559577, 2021). "Ultimately, our findings confirmed that miR-4269 served as a cancer suppressor in PC through regulation of ZEB1/OTX1 pathway, which suggested that miR-4269 might represent a promising target for the clinical treatment of PC." (PMID 32484209, 2020). "OTX1 KD in GC cell lines caused a reduction in proliferation, with cell cycle arrest in the G0/G1 phase and less migration and invasion via the reduction of the expression of mesenchymal markers and EMT-related transcription factors, a critical step involved in cancer metastases." (PMID 38069286, 2023). "This is a significant finding because it suggests that OTX1 plays a role in the development or progression of PTC, offering a new avenue for understanding the molecular mechanisms of this type of cancer." (PMID 37780815, 2023). "Our findings contribute to the understanding of OTX1's involvement in PTC and align with the existing literature on the functional significance of transcription factors in cancer." (PMID 37780815, 2023). "Both the Rb subtypes expressed the cone-specific markers RXR γ, CRX, OTX1, and TRβ2 (data not shown), compared to the pediatric retina, supporting the cone photoreceptor origin of cancer." (PMID 35626705, 2022).
cancer (continued). "For early-stage cancers, DNA methylation-based biomarkers are of particular importance Recent scientific work indicates the high potential of hypermethylated genes TWIST1, VIM, ZNF671, OTX1, and IRF8 for early diagnosis and PTK2, AHNAK, and DAPK for BC prognosis." (PMID 39685620, 2024). "When OTX1 expression is silenced, the cell proliferation ability and the expression level of related protein p-ERK are reduced, indicating that the role of OTX1 in cancer cells may depend on the activation of p-ERK." (PMID 35771766, 2022).
infection (1 paper, 2018). The state of being infected such as from the introduction of a foreign agent such as serum, vaccine, antigenic substance or organism. "Transcription factors, such as ZNF503, ZNF283, DYM, and OTX1, that control genes involved in antiviral defense may affect downstream targets at later infection stages." (PMID 29997306, 2018).
OTX1 also shares sentences with these, for which no sentence is quoted: autism (2 papers); cervical carcinoma (2); sinonasal carcinoma (2); adenocarcinoma (1); brain tumors (1); Burkitt lymphoma (1); chronic lymphocytic leukemia (1); clear cell renal cell carcinoma (1); colon (1); coronary heart disease (1); diffuse large B-cell lymphoma (1); endometrial cancer (1); follicular lymphoma (1); glaucoma (1); glioma (1); hydronephrosis (1); ischemia (1); lung adenocarcinoma (1); mantle cell lymphoma (1); microdeletion syndromes (1); Micropenis (1); multiple myeloma (1); nasopharyngeal carcinoma (1); neuroblastoma (1); neurodevelopmental disorder (1); non-small cell lung carcinoma (1); proliferative vitreoretinopathy (1); Sandhoff disease (1); sitosterolemia (1); squamous cell carcinoma (1).
A further 1 disease shares a sentence with OTX1 in 1 paper.